TRPM8 (transient receptor potential cation channel subfamily M member 8)
Diseases named in the same sentence as TRPM8 in open-access papers (continued):
Sharing a sentence is not in itself a finding about the gene and the disease.
colitis (22 papers, 2015 to 2025). Inflammation of the colon. "Accordingly, we demonstrated that genetic ablation of TRPM8 induces a pro-tolerogenic profile in macrophages in vitro, and reduces colitis susceptibility in vivo, revealing the critical importance of this receptor in innate immunity." (PMID 40280909, 2025). "Adoptive transfer of TRPM8-deficient bone marrow in wild-type mice improved intestinal inflammation in a model of colitis." (PMID 40280909, 2025). "TRPM8-deficient mice exhibit increased susceptibility to colitis, a phenotype rescued by systemic IL-10 expression." (PMID 37404813, 2023). "The activation of TRPM8 with icilin significantly attenuated the experimental colitis, but Trpm8−/− mice were quite susceptible to colitis." (PMID 32153564, 2020). "Finally, the reconstitution of wild-type mice with Trpm8-deficient BM resulted in reduced severity of DSS-induced colitis." (PMID 40280909, 2025). "In contrast, TRPM8-deficient mice showed increased susceptibility to colitis." (PMID 38731999, 2024). "In addition, other experiments also identified augmented CGRP levels in TRPM8-deficient colitis mice." (PMID 39062591, 2024). "However, other studies have shown that visceral hyperalgesia in colitis may be linked to elevated TRPM8 expression, and the administration of WS-12 can trigger a visceral pain-like response that is counteracted by the TRPM8 inhibitor AMTB hydrochloride." (PMID 39062591, 2024). "Furthermore, the adoptive transfer of TRPM8-deficient macrophages was found to exacerbate colitis." (PMID 38731999, 2024). "Previous research has demonstrated that TRPM8 suppresses the development of colitis induced by trinitrobenzene sulfonic acid (TNBS) or DSS in mice." (PMID 40053041, 2025). "TRPM8, a key temperature and nociceptive receptor in sensory neurons, possesses the capacity to alleviate colitis." (PMID 40053041, 2025). "Overall, these findings reveal a previously unexplored mechanism by which COP diminishes inflammation in colitis, specifically through the TRPM8 signaling pathway." (PMID 40053041, 2025). "The study on a DSS-induced colitis model has demonstrated that wild-type mice treated with repeated menthol (TRPM8 agonist) enemas were protected from DSS colitis." (PMID 38731999, 2024). "TRPM8 is one of the most important temperature and nociceptive receptors in sensory neurons, and it has the ability to alleviate colitis." (PMID 38280896, 2024). "To elucidate the TRPM8 role in colitis, we administered TRPM8 agonist (menthol) and/or antagonist (AMTB) via enema to the DSS-treated mice." (PMID 38280896, 2024). "It was found that TRPM8 activation by its agonist icilin results in anti-inflammatory effects in a mouse model of DSS-induced colitis." (PMID 38731999, 2024). "Although consistent anti-inflammatory effects of TRPM8 in colitis are observed across studies, further research is warranted to elucidate the precise underlying mechanisms." (PMID 39062591, 2024). "Our study aimed to investigate TRPM8’s role in SP release from primary sensory neurons during colitis and clarify the effect of SP on colonic epithelium." (PMID 38280896, 2024). "Previous study revealed that TRPM8 attenuates TNBS- or dextran sulfate sodium (DSS)-induced colitis in mice." (PMID 38280896, 2024). "Whereas TRPM8 activation induced the opposite effect in vivo, activating TRPM8 by repeated menthol enemas protects mice from experimental colitis." (PMID 37404813, 2023). "In vivo, menthol (TRPM8 agonist) enema increased in the anti- inflammatory cytokine profile of M2 macrophages, which had a protective effect on mice with experimental colitis." (PMID 37404813, 2023). "Numerous studies examining the role of TRPM8 in inflammatory conditions, such as chronic neuropathic pain, noxious cold, and colitis, have demonstrated an upregulation of TRPM8 expression." (PMID 33193423, 2020).
colitis (continued). "Macroscopically, the simultaneous treatment of TRPM8 agonist icilin with TNBS and DSS appeared to substantially diminish colitis-associated histological damage in comparison to TNBS and DSS treatment alone." (PMID 33193423, 2020). "In preclinical murine models of colitis, TRPM8 appears to regulate inflammation through direct mediation of inflammatory cytokines." (PMID 33193423, 2020). "The reconstitution of Trpm8−/− macrophages in mice exerted a deleterious effect on DSS-induced colitis, exhibiting a protective property of TRPM8 in macrophages." (PMID 32153564, 2020). "Significant upregulation of TRPM8 expression was observed in both chemically induced colitis within mice (trinitrobenzene sulfonic acid; TNBS– and DSS-treatment) and non-inflamed colonic tissue from Crohn’s disease patients." (PMID 33193423, 2020). "Two recent reports, however, favor a dominant role for TRPM8 expression in controlling neuropeptide release and, thus, colitis development." (PMID 29467763, 2018). "Enemas with the TRPM8 agonist WS-12 induced behavioral visceral pain-like responses which were much greater in mice with colitis compared to controls and were decreased by pretreatment with the TRPM8 antagonist AMTB." (PMID 26207981, 2015). "In agreement, a recent study supports a pronociceptive role of TRPM8 in colitis-induced visceral hyperalgesia in mice." (PMID 26207981, 2015). "COP ameliorated colitis in mice by regulating the cPLA2/TRPM8/CGRP-1 pathway, strengthening intestinal barrier function, and modulating inflammatory mediators, which was supported by network pharmacology analysis, offering novel insights into its protecting mechanism." (PMID 40053041, 2025). "Taken together these data indicate that TRPM8 deletion from immune cells in mice, as well as luteolin supplementation, counteracts intestinal inflammation and mediates an impairment in the innate immune response during experimental colitis." (PMID 40280909, 2025). "In colitis, for instance, although TRPM8 consistently exhibits anti-inflammatory properties across studies, the precise mechanism of its action remains unclear, possibly influenced by study design." (PMID 39062591, 2024). "Moreover, another study of UC (GSE47908) revealed that TAC1 expression was significantly higher in patients with pancolitis than in those with left-sided colitis and normal individuals, whereas TRPM8 showed the opposite trend." (PMID 38280896, 2024). "This study posited that the heightened number of TRPM8 nerve fibers in colitis model mice mucosa, coupled with the co-localization of TRPM8 with CGRP and SP in nerve fibers, may underlie this association." (PMID 39062591, 2024). "The activation of TRPM8 attenuated DSS-induced colitis in mice." (PMID 38280896, 2024). "In addition, TRPM8 activation has been shown to attenuate inflammatory responses in mouse models of colitis, while Trpm8 mouse knockouts are hypersensitive to chemical-induced colitis." (PMID 37623246, 2023). "Inflammation in mouse colitis models can be alleviated by the activation of TRPM8." (PMID 37402746, 2023). "Although TRPM8−/− mice are more likely to experience colitis, studies have found that loss of TRPM8 can not cause intestinal barrier dysfunction or epithelial cell tissue destruction." (PMID 34135754, 2021). "Besides its role in cold sensation, TRPM8 is also involved in the suppression of inflammatory responses in colitis, experimental autoimmune encephalomyelitis, and the augmentation of airway inflammatory diseases." (PMID 34589786, 2021). "However, evidence in mouse experimental colitis models has suggested protective effects of TRPM8 activation in colonic inflammation." (PMID 32751347, 2020). "Transient receptor potential cation channels are present in immune cells because it is considered that the anti-inflammatory action of PO may be regulated by the activation of transient receptor potential melastatin 8 (TRPM8), which downregulates chemical-induced colitis in mouse models." (PMID 40430512, 2025).
colitis (continued). "However, a reduced absolute number of immune cells in the colonic lamina propria of luteolin-treated mice was observed during the recovery phase after induction of colitis compared with the vehicle group, mirroring the effect of TRPM8 conditional immune genetic deletion." (PMID 40280909, 2025). "However, these previous reports on monocytes/macrophages mainly discussed about the function of TRPM8 in regulating inflammation in the context of colitis model or LPS stimulation, which might be different from the context of cold stress." (PMID 41168503, 2025). "However, its effect on colonic primary sensory neurons remains unclear, and may be an important mechanism by which TRPM8 alleviates colitis." (PMID 38280896, 2024). "Indeed, icilin treatment significantly attenuates induced colitis in wildtype mice, but not in TRPM8 deficient ones." (PMID 32751347, 2020). "The search terms used were "Transient Receptor Potential Channels", "TRP channels", "TRPV1", "TRPA1", "TRPV4", "TRPV2", "TRPM2", "TRPM3", "TRPM7", "TRPM8", "TRPC3", "colitis", "inflammatory bowel disease", "IBD", "ulcerative colitis", "Crohn Disease"." (PMID 41096659, 2025). "Our study found that TRPM8, TAC1 and WNT3A expression were significantly correlated with the severity of ulcerative colitis in patients and DSS-induced colitis in mice." (PMID 38280896, 2024). "Increased number of TRPM8-expressing nerve fibers has been shown to contribute to visceral hyperalgesia in mouse models of DSS- and TNBS-induced colitis." (PMID 38731999, 2024). "The results showed that Trpm8 and Tac1 expression were significantly decreased and increased, respectively in the DSS-induced colitis group." (PMID 38280896, 2024). "Finally, we could recently show that mice that were reconstituted with TRPM8-deficient macrophages exhibited increased susceptibility to DSS, demonstrating a fundamental role of constitutive TRPM8 expression in macrophages in the context of colitis." (PMID 29467763, 2018). "Administration of TRPM8 agonists in the colitis models inhibited TRPV1-dependent CGRP expression, reduced pro-inflammatory cytokines, and attenuated the common hallmarks of colitis such as bowel thickness and infiltration of granulocytes." (PMID 30087301, 2018). "Notably, CGRP administration mitigated colonic inflammation, demonstrating TRPM8/CGRP co-expression in human and wild-type mouse colonic mucosal fibers, accentuated during colitis." (PMID 39062591, 2024). "Both the TRPM8 agonist menthol and the SP receptor antagonist Aprepitant can attenuate colitis in mice, but the effects were not additive." (PMID 38280896, 2024). "The TRPM8 agonist (menthol) and the SP receptor antagonist (Aprepitant) can attenuate colitis in mice, but the effects were not additive." (PMID 38280896, 2024). "Conclusively, TRPM8 inhibits SP release from primary sensory neurons by inhibiting the interaction between PKAca and GSK-3β, thereby inhibiting the role of SP in promoting colonic epithelial apoptosis and relieving colitis." (PMID 38280896, 2024). "Systemic activation of TRPM8 by icilin suppresses intestinal inflammation in wild-type mice but not in TRPM8 KO mice in chemically induced colitis models." (PMID 36459135, 2023). "Unlike the analgesic effects produced in colitis or nerve injury, TRPM8 function in the lungs triggers bronchial inflammation through prolonged cold air inhalation." (PMID 33193423, 2020). "TRPM8 is thought to have a role in the inhibition of visceral pain signals and reduction of inflammatory conditions in irritable bowel syndrome (IBS) as TRPM8 activation reduces colon inflammation both in animal models and human subjects." (PMID 32751347, 2020). "It was also demonstrated that icilin, a specific TRPM8 agonist, attenuates TRPV1-dependent calcitonin gene-related peptide release in the colon and is suggested as a promising therapeutic target for the treatment of colitis." (PMID 30298050, 2018).
colitis (continued). "Moreover, the results of network pharmacology have validated existing literature and our experimental findings, thereby confirming the TRPM8 signaling pathway and inflammatory factors such as TNF-α, IFN-γ, and IL-6 as pivotal components in the regulatory role exerted by COP on DSS-induced colitis." (PMID 40053041, 2025). "Experiments shown that both TRPM8 agonist menthol and SP receptor antagonist Aprepitant could alleviate colitis in mice, but they could not be superimposed, which verifies the role of TRPM8 in attenuating colitis by inhibiting SP release." (PMID 38280896, 2024). "However, according to existing data on other TRP channels and the observed effects in animal colitis models, there is a need to study positive/negative events associated with TRPM2, TRPM3, TRPM8, and TRPV2 channels in humans." (PMID 38731999, 2024). "Besides TRPA1/TRPV1, TRPM8 is also functionally expressed by the colon-innervating DRG neurons and TRPM8 expression is upregulated in inflamed colon samples from both human and mouse models of DSS- and TNBS-induced colitis." (PMID 36459135, 2023). "It has been revealed that TRPM8 activation leads to a decline in TRPV1 activity, which may be of therapeutic benefit in clinical circumstances such as treatment of TRPV1-mediated inflammatory hyperalgesia, colitis, and dry eye syndrome." (PMID 28861042, 2017). "Further studies are required, including other TRP channels (e.g., TRPM2, TRPM3, TRPM8, TRPV2), which have demonstrated beneficial or negative effects on intestinal inflammation in animal models of colitis, to confirm/refute the severity of these effects in humans." (PMID 38731999, 2024).
Obesity (20 papers, 2017 to 2025). Accumulation of substantial excess body fat. "Contrarily, mice deficient in TRPM8 (the main cold sensor) develop obesity when housed at mild temperatures, exhibiting diurnal hyperphagia, reduced lipid utilization and an altered circadian physiology." (PMID 36967809, 2023). "Recently, it has been demonstrated that TRPM8-deficient mice develop late-onset obesity and metabolic dysfunction at moderate cooling, suggesting the importance of TRPM8 in the coupling between thermoregulation and energy homeostasis." (PMID 30298050, 2018). "Furthermore, sustained alterations in the function of certain thermoTRP channels (e.g.,TRPM8 polymorphisms) may play an unrecognized role in obesity pathogenesis." (PMID 36967809, 2023). "In our recently published manuscript, we have shown that the oral and topical administration of menthol, a TRPM8 agonist, has anti-obesity potential through a TRPM8 mediated glucagon dependent mechanism." (PMID 31027377, 2019). "Recently we have published that anti-obesity effect of menthol, a TRPM8 agonist is mediated through glucagon dependent mechanisms particularly in adipose tissues." (PMID 31027377, 2019). "Chronic TRPM8 agonist administration enhances the energy metabolism in brown adipocytes and prevents obesity in mice." (PMID 30298050, 2018). "Now, by revealing a potent anti-obesity potential of the TRPM8 agonist icilin, we add substantial support to this idea." (PMID 30353008, 2018). "Conclusively, these data support the compelling potential in coordinated targeting of TRPM8 and α3β4-nAChRs for the treatment of the related epidemics of obesity, type 2 diabetes, and fatty liver disease." (PMID 30353008, 2018). "Targeting TRPM8 to increase energy expenditure as a means to combat obesity has previously been suggested." (PMID 30353008, 2018). "Moreover, deletion of TRPM8 induces obesity and reduces fatty acid oxidation in mice housed in mild cold temperatures." (PMID 39087083, 2024). "As an activator of TRPM8, menthol might be a promising candidate for the treatment of obesity and other metabolic diseases." (PMID 35886989, 2022). "Furthermore, TRPM8 is a potential target for obesity treatment due to its function in regulating energy metabolism." (PMID 34086678, 2021). "In summary, activation of TRPM8 by its ligands, such as menthol and icilin, mimics adipocyte thermogenesis and might constitute a promising approach to prevent overweight and obesity." (PMID 34249940, 2021). "Moreover, Trpm8 knockout (Trpm8-KO) mice are hyperphagic and have reduced fat oxidation when housed at 21°C, promoting the development of obesity." (PMID 34086678, 2021). "We hypothesize that different TRPM8 dependent and independent actions are contributing to the anti-obesity effect of menthol." (PMID 31027377, 2019). "Briefly, our data strongly indicate that pharmacological activation of cold receptor TRPM8 by menthol plays an important role in energy homeostasis via activation of glucagon machinery which provides an additional mechanism for TRPM8 activation induced prevention of obesity and related conditions." (PMID 30505271, 2018). "Therefore, targeting the TRPM8 channel could potentially be a viable intervention for improving both obesity management and skeletal muscle function." (PMID 39764565, 2025). "However, it is unknown whether TRPM8 has a role in regulating bone density in vivo and by inference, whether modulation of TRPM8 by obesity therapeutics might influence bone." (PMID 34086678, 2021). "Therefore, enhancement of TRPM8 activities by dietary food, such as menthol, could pave an intriguing way for the treatment and prevention of human obesity and related metabolic diseases." (PMID 29088850, 2017). "Administering menthol activates TRPM8, leading to increased UCP‐1 expression and thermogenesis, which raises body temperature and provides protection against obesity in both mice and humans." (PMID 39764565, 2025).
Obesity (continued). "By activating TRPM8 with agonists such as menthol, HFD fed mice are protected against obesity and glucose intolerance." (PMID 39087083, 2024). "Combinatorial targeting of TRPM8 and nAChR α3β4 by icilin and dimethylphenylpiperazinium (DMPP) orchestrates synergistic anorexic and thermogenic pathways to reverse diet-induced obesity, dyslipidemia, and glucose intolerance in DIO mice." (PMID 30353008, 2018). "And menthol-induced TRPM8 activation resulted in [Ca2+]i increases, which further led to sWAT “browning” and reduced body weight gain and insulin resistance in HFD-induced obesity mice." (PMID 29088850, 2017). "Our data suggest that long-term and localized inhibition of TRPM8 by AMTB can be useful for reducing LD volume and thus may prove useful for treating obesity." (PMID 41202880, 2025). "Studies have shown that inducing the transient receptor potential cation channel, subfamily M, member 8 (TRPM8) activation by dietary menthol might enhance the WFB and improve the diet-induced obesity." (PMID 35886989, 2022). "This study suggested that activation of TRPM8 enhances BAT thermogenesis, which could offer promising approaches to treat and prevent obesity." (PMID 29088850, 2017). "Menthol treatment partially prevented diet-induced obesity and insulin resistance; these effects were not seen in TRPM8 knockout mice." (PMID 29070564, 2017). "With the recent reports that TRPM8 is expressed in human WAT, menthol-induced TRPM8 activation could mimic cold stimulation-induced thermogenesis and could constitute an intriguing approach to treat human obesity and related metabolic disorders." (PMID 29088850, 2017). "Thus, chronic dietary menthol increased thermogenesis, core body temperature, prevented diet-induced obesity and the abnormal glucose homeostasis in wild-type mice but not in UCP1(−/−) and TRPM8(−/−) mice, suggesting TRPM8 receptor presence on adipose tissue is essential." (PMID 31027377, 2019).